TLR7 (toll like receptor 7)
Diseases named in the same sentence as TLR7 in open-access papers (continued):
Sharing a sentence is not in itself a finding about the gene and the disease.
infection (continued). "Moreover, mRNA levels of Toll-like receptor 7 (TLR7) and Interferon-b (IFN-b) significantly increased in the lungs post-infection." (PMID 39114658, 2024). "Treatment with melatonin at 250 μM before and after infection significantly reversed the induction of TLR3 (p < 0.05) and TLR7 (p < 0.01) mRNA levels and suppressed the expression of NF-κB (p < 0.05), COX-2 (p < 0.05) and TNF-α (p < 0.001) induced by JEV infection." (PMID 37055489, 2023). "These demonstrated that TLR7 modulates splenic erythropoiesis but not bone marrow erythropoiesis through an indirect way after the infection." (PMID 37180169, 2023). "Combination of a TLR7 agonist and bNAb was able to prevent viral rebound after treatment discontinuation in a subset of Macaca mulatta infected with SHIV-SF162P3 and treated since the chronic stage of infection." (PMID 36678440, 2023). "It is largely recognized that TLR7 expression in innate immune cells, particularly plasmacytoid DCs (pDCs), is essential for inducing the IFN-I response, which is required to control HIV spread during the acute phase of infection." (PMID 37227774, 2023). "We modelled infection (4 h and 24 h) using the bacterial PAMP, lipopolysaccharide (LPS; a toll-like receptor [TLR]-4 ligand) or the viral PAMPs, polyinosinic polycytidylic acid (Poly I:C; TLR-3 ligand) and single-stranded RNA (ssRNA; TLR-7/8 ligand)." (PMID 36721242, 2023). "Taking into account RNA seq and ribo-seq data on SARS-CoV-2 RNA expression and translation during infection, we selected 3 out of the 9 candidate SARS-CoV-2 RNA fragments determined by BrainDead to activate TLR7/8 and being located to distinct SARS-CoV-2-derived genomic regions." (PMID 36713399, 2022). "While basal expression of these receptors and integrins was comparable in all groups of uninfected mice, CCR9 and CX3CR1 were significantly upregulated on pDC after infection in WT but not in Tlr7−/y mice." (PMID 36278864, 2022). "In the infection scenario, the combination—but not the products alone—was able to increase the expression of TLR7 and TLR9 genes." (PMID 35334820, 2022). "At 7th day post challenge, TLR5, TLR7, il6, il1b, and IL12B were still highly expressed, suggesting that TLR may play a role in both early and late stages of infection." (PMID 36439120, 2022). "Notably, as a key factor in intracellular pathogen recognition, toll-like receptor 7 was expressed in the kidney and spleen at 6 h and 48 h after GSIV infection, respectively." (PMID 36012277, 2022). "Here, we observed significantly increased TLR7 mRNA expression in PBMCs of patients with HCV infection compared to those without infection (P < 0.005)." (PMID 34724826, 2021). "TLR7 is a single-stranded ribonucleic acid (ssRNA) sensor, also involved in the host response to SARS-CoV-2, and activation is likely to occur during infection with other ssRNA viruses." (PMID 33553478, 2021). "This increased expression suggests that TLR7 and TLR8 may be more relevant than TLR3 in modulating infections with hMPV." (PMID 33809875, 2021). "The lack of differential expression of other TLR genes in this study is in contrast to a previous study of transcriptomic response of ovine PBMC conducted by our group, where TLR1, TLR5, TLR6, TLR7 and TLR10 were downregulated in PBMC at the acute stage of infection." (PMID 34616397, 2021). "When viral genomic RNA is internalized and released into the cytoplasm after infection, the RNA is recognized by cellular RNA sensors such as stimulator of interferon response cGAMP interactor 1 (STING), Toll-like receptor 7 (TLR7), DExD/H-box helicase 58 (RIG-I), and others." (PMID 32709063, 2020). "A further study found that after autophagy is suppressed by pretreating with 3-methyladenine (3-MA), EVA71 infection fails to inhibit the expression levels of TLR7-signaling-related molecules." (PMID 33298183, 2020).
infection (continued). "During infection with SARS-Cov-2, which has a single strand RNA genome, both TLR3/TLR7 senses the presence of viral RNA, the mimic induced CSS in lung may not affect by blocking of TLR3 signaling." (PMID 33584719, 2020). "We next assessed if adjuvant TLR7/8/9 stimulation impacted on HIV-1 replication during productive infection (no fusion block)." (PMID 31919342, 2020). "Interestingly, infections of these mice with TMEV and the related Coxsackie virus, which are known to activate several TLR-mediated signals, including TLR2, TLR3, and TLR7, significantly accelerated the development of autoantibody production." (PMID 32727036, 2020). "To determine the PRRs and cytokine levels following the infection of the H5N6 viruses at the early stage, we further measured the expression of the TLR3, TLR7, RIG-I mRNA, and a set of representative cytokines in the brains and lungs of mice at 3 and 5 DPI using qRT-PCR." (PMID 31717638, 2019). "Western blot experiment results showed that, at the 3rd and 7th days after infection, protein expression levels of TLR4, TLR7, MyD88 and NF-κB p65 in the murine lung tissues of the control infected group were significantly higher than those in the control uninfected group (all P < 0.01)." (PMID 31551774, 2019). "Since we observed an essential function of TLR7 in the development of early VSV infection in dLN, we queried whether this is also required at the very first site of infection." (PMID 30930901, 2019). "Pneumonia virus of mice (PVM) infection led to a marked infiltration of pDCs and increased expression of type I IFN in WT but not TLR7- or MyD88-deficient mice." (PMID 31031767, 2019). "As such, TLR2, TLR3, TLR4, TLR7, TLR8, and TLR9 are known to recognize EBV during infection." (PMID 31238570, 2019). "The induction of cytokines (IL6 and TNFα), chemokines (CCL2 and CXCL10), and IFN-I genes in primary C57BL/6 astrocytes following a TMEV-BeAn infection can be mediated by TLR3 but not TLR7 or other MyD88-mediated pathways." (PMID 30669615, 2019). "Higher TLR-7 levels were found in infection patients than in the gout and HC groups (0.46 vs 0.28 vs 0.30 ng/ng B2M, p<0.05), whereas lower TLR-9 levels were found in sepsis than infection and HC groups (0.015 vs 0.034 vs 0.025 ng/ng B2M, p<0.05)." (PMID 30890150, 2019). "Although HIV completely inhibits the IRF3-mediated IFN-I response in myeloid DCs, macrophages and CD4+ T cells upon uptake or infection, pDCs constitutively express high levels of IRF7 and upon sensing endosomal HIV ssRNA through TLR7, IFN-I production is rapidly and potently induced." (PMID 31156637, 2019). "Our results indicated that S. japonicum infection could induce the TLR7 expression on T cells in the MLN of C57BL/6 mice, and TLR7 mediates T cell response in the early phase of infection." (PMID 31930147, 2019). "While rapid type I IFN production in pDCs was observed following infection with mouse hepatitis virus (MHV), a betacoronavirus, its induction was abrogated in TLR7−/− or MyD88−/− MHV-infected mice, indicating that MHV-mediated type I IFN induction in pDCs was triggered via the TLR7/MyD88 pathway." (PMID 30854373, 2019). "In contrast, our data demonstrate that neither cell-specific deletion of TLR7 in skin-derived Langerin+ cells nor complete ablation of Langerin+ cells in the foot skin prior to infection reduces the VSV titers in pLN." (PMID 30930901, 2019). "Infection with S. Typhimurium and S. Dublin led to a significant downregulation of TLR2, TLR3, TLR4, TLR5, and TLR7 in chicken macrophages HD11, whereas only a slight downregulation of TLR3 and TLR7 genes was observed in the S. Gallinarum infection group." (PMID 31998655, 2019). "To determine the PRRs and cytokine levels following the infection of the H5N6 viruses at the early stage, we further tested the expression of TLR3, TLR7, MDA5 mRNA and a set of representative cytokines in the brains and lungs of chickens at 24 h postinfection using qRT-PCR." (PMID 31717638, 2019).
infection (continued). "Our data suggests that TLR7 signaling in SCS macrophages supports VSV replication in these cells, increasing LN infection and may account for the delayed onset of VSV-induced neurovirulence observed in TLR7−/− mice." (PMID 30930901, 2019). "During the later stage of infection (60 hpi, 72 hpi), TLR3 and TLR7 expression gradually increased." (PMID 29700351, 2018). "This redundancy can also be seen in the activation of TLR7; neither activation of TLR3 nor TLR7 alone appear capable of stimulating IFN-mediated antiviral defense during infection." (PMID 29552008, 2018). "In conclusion, this study demonstrates that different degrees of autophagy induced by EV71 and CA16 infection hinders IFN-I production by promoting endosomal degradation and inhibiting the TLR7 signaling pathway, ultimately leading to successful replication of EV71 and CA16 in host cells." (PMID 29052054, 2018). "Therefore, wild type and TLR7 KO mice were infected with Influenza FM1 virus, and four drugs were used to treat the mice 24 h after infection, respectively." (PMID 30151032, 2018). "Based on these TLR7-dependent changes observed in the lung in the early phase of IAV infection, we further assessed the kinetics of NK cell activation at the site of infection by analyzing lung NK cells from IAV-infected WT and TLR7ko mice for the expression of the early activation marker CD69." (PMID 29497422, 2018). "By detecting extracellular T. cruzi through TLR2 and TLR4 at the moment of the infection, or intracellular T. cruzi through TLR9 and TLR7, the cardiomyocytes should activate the MyD88 pathway and induce CCL5 that will focus the recruitment of cytotoxic CD8+ T cells towards the infected cell." (PMID 30067739, 2018). "Furthermore, it was found that TLR4 and nucleolin levels increased early after infection and decreased subsequently, whereas TLR3 and TLR7 expression increased throughout RSV infection." (PMID 29427996, 2018). "Next, we questioned whether as observed for spleen and heart tissue during infection, ONX 0914 treatment influences cytokine/chemokine production also in TLR7‐activated BMM." (PMID 29295868, 2018). "The results indicated that TLR-7 mRNA increased at 24 h in SD-PJEC cells infected with IA07 while MN08 infection did not alter the gene expression." (PMID 29880757, 2018). "To determine if TLR7 was important for IFN-β expression in vivo, we studied Y. pestis KIM D27 (T3SS+pgm negative) infection of Tlr7−/− mice." (PMID 28847850, 2017). "Similarly, Tlr7−/− BMDMs also expressed higher levels of IFN-β when infected with the ΔphoP mutant, with an approximately 9-fold increase over that induced by infection with KIM6, suggesting that one or more other PRRs are activated by the ΔphoP mutant." (PMID 28847850, 2017). "To examine if TLR7/8/MyD88 signaling affects intracellular Mav growth we next quantified Mav-CFP intensities across infected macrophages at the single cell level 4 hours and 3 days post infection." (PMID 28806745, 2017). "In TLR7−/− mice, JEV infection induced higher levels of pDC and improved the responses of JEV-specific CD4+ and CD8+ T cells involved in viral clearance during the early and late phases of infection, respectively." (PMID 28265274, 2017). "ELISA analyses revealed that CSF3, IL-1β, and IL-6 proteins were induced by EV71 or R848 (a TLR7 agonist) as a stimulus control, but not by mock-infection or UV-inactivated EV71, in THP-1, macrophages, and human PBMCs." (PMID 28854257, 2017). "WT and Tlr7−/− BMDMs expressed approximately 30% less IFN-β during infection by the Δspa mutant than during infection by WT S. aureus Newman, but this difference was not significant." (PMID 28847850, 2017). "Activation of TLR7 signaling pathways ultimately leads to the release of antiviral and proinflammatory cytokines, such as type I interferons (IFN-α and IFN-β), that help the host rapidly mount an immune response to infection with an invasive pathogen." (PMID 27799218, 2017).
infection (continued). "Furthermore, most of the immune-related genes, particularly TLR7, TRAF3, Mx, TRIM25, CD4, and CD8α, increased in response to GPV and H9N2 infection." (PMID 27916934, 2016). "The small percentage of TLR7/9-/- mice that did not succumb to infection by 14 dpi displayed unusual behavior, such as rapid movements, walking backwards, and running into the sides of the cage." (PMID 27459510, 2016). "In addition, the expression levels of TLR1, TLR2, TLR7, and TRAF3 were significantly increased in response to GPV and H9N2 infection." (PMID 27916934, 2016). "Absence of TLR7 in T cells leads to the impaired T-bet expression in B cells and subsequent inefficient IgG2a isotype switching both in vitro and during the infection with Friend virus in vivo." (PMID 27880772, 2016). "In contrast, BMMs do not induce IFN-I in response to infection with Histoplasma yeasts, and TLR7/9 do not influence the fate of infected macrophages." (PMID 27459510, 2016). "TLR7/9-/- mice produce increased levels of IL6, TNF-α, and IL17A during Histoplasma infection, and similar results have been observed for the endemic fungal pathogen P. brasiliensis during infection of TLR9-/- mice." (PMID 27459510, 2016). "Allergic Tlr7−/− mice received recombinant type I and III IFNs 2 h after infection with RV." (PMID 26108570, 2015). "Compared to the mock-infected ducks at 24 hpi, the lungs of SS-10-infected ducks during the first 3 days of infection showed upregulation that peaked in the mRNA expression level of TLR3 (95.36-fold), TLR7 (146.35-fold), RIG-I (26.29-fold), MDA5 (4.22-fold), and LGP2 (4.77-fold)." (PMID 26635752, 2015). "The percentage of γδ T cells was also increased in MyD88−/−or TLR7−/− mice at day 3, but became not significant at day 5 following infection (P>0.05)." (PMID 25232836, 2014). "In contrast to infection with LV, infection with Lena down-regulated the pathways involved in the interplay between the innate and adaptive immune response, cell death and TLR3/TLR7 signaling." (PMID 24643046, 2014). "Type I IFNs are also produced by plasmacytoid dendritic cells (pDC) after sensing of HIV and HCV through TLR7 in the absence of productive pDC infection." (PMID 24788318, 2014). "While our studies showed that mDCs isolated from PTMs show a similar hyporesponsiveness postinfection to TLR7/8 stimulation compared to nonprogressive infections, mDC activation was significantly higher in PTMs." (PMID 24098110, 2013). "In contrast, during 24 hours of RSV infection, the levels of TLR3-4 and TLR7-8 were increased from 3 h after RSV infection, and reached to the highest levels at 24 h after infection, whereas TLR9 expression reached a peak level at 12 h after infection with RSV, and then declined." (PMID 24039959, 2013). "It will be important to determine whether TLR7- and TLR9-driven activation of pDC plays any role in immune activation in the chronic stages of infection when disease is manifest." (PMID 23935491, 2013). "Based upon these data, we speculate that the suppression of TLR7/8-mediated TNF-α and IL-6 expression by MSC-conditioned medium modulates the pathogenesis of ssRNA virus infection, including infection by influenza virus." (PMID 24191131, 2013). "Upon infection, HPV further down-regulate TLR7 and 9 levels for viral persistence." (PMID 22513098, 2012). "Therefore, the mechanism(s) for the suppression vs. partial reduction of infection upon TLR3/4 and TLR7/9 engagement, respectively, remained unclear." (PMID 23028330, 2012). "We found that poly(I∶C)- and LPS-stimulation of MDMs abrogated infection by CCR5-using, macrophage-tropic HIV-1, and by vesicular stomatitis virus glycoprotein-pseudotyped HIV-1 virions, while TLR2, TLR7 or TLR9 agonists only partially reduced infection to varying extent." (PMID 23028330, 2012).
infection (continued). "Furthermore, we found that IFI16 is upregulated by type I IFN and by the nuclear factor kappa B (NF-κB)-activating TLR7/8 agonist R848; yet, it is only slightly upregulated by HSV-1 during very early infection." (PMID 23062757, 2012). "We demonstrate that the lack of TLR7 signaling significantly increases the accumulation of MDSCs at the site of infection." (PMID 21966467, 2011). "This might indicate that the TLR4 signalling pathway may be less affected than the TLR7 and TLR9 signalling in Dogon undergoing infection." (PMID 21483827, 2011). "In a situation where TLR7 is not present, MDSCs would lose their ability to sense the presence of RNA during an ongoing infection." (PMID 21966467, 2011). "Remarkably, B cells in infected TLR7-deficient mice upregulated CD69 and CD86 early in infection, but failed to develop into germinal center B cells." (PMID 21998589, 2011). "This suggests that increased IRF-5 expression in T-cells is independent of TLR7 during the early stages of infection in the liver." (PMID 21253574, 2011). "However, in the case of RABV it appears that MyD88-dependent signaling, and thus TLR-7, is dispensable for IFN-α/ß production following infection." (PMID 20661430, 2010). "The response of dendritic cells to VSV seems to be restricted to TLR7+ DC, as no IFN-α/β production is seen following infection of myeloid DCs that do not express TLR-7." (PMID 21994572, 2009). "Between 20% and 40% of pDC in blood produced TNF-α in response to TLR7 stimulation regardless of infection status." (PMID 19424421, 2009). "Monitoring the expression of RNA-sensing receptors like TLR3, TLR7 and RIG-I during the different clinical stages of infection could bring a new source of data about the prognosis of disease." (PMID 18021446, 2007). "IL-6 and IL-10 secretion was not altered by TLR7/8 stimulation prior to infection." (PMID 41974867, 2026). "Additionally, infection with H9N2 AIV, whether live or inactivated, induces strong innate antiviral and inflammatory responses involving TLR3, TLR7, MDA5, TNF-α, and CCL5 stimulation." (PMID 41331407, 2025). "This feature of TLR‐7 likely explains why the 4 P. nobilis introgressed with a partial TLR‐7 of P. rudis could not effectively resist the infection with H. pinnae, whereas those with a full‐length P. rudis TLR‐7 were not affected." (PMID 37546570, 2023). "While TLR7 suppressed inflammatory markers in the nasal tissue, this enhanced the progression of inflammation and immune infiltration in the LRT, which added little benefit to the host response to infection, but rather expedited long-term immunopathological consequences." (PMID 37795093, 2023). "In lethal Plasmodium yoelii YM infection, it’s plasmacytoid cells (pDCs) that sense the infection through TLR7 and produce a large amount of IFN-α and IFN-β via Myd88-dependent IFN regulatory factor (IRF) 7 transcription factor-mediated type I IFN signaling in the first 24 hours post infection." (PMID 37180169, 2023). "The activation of TLR7 does not occur in the same way at subsequent infections." (PMID 35632732, 2022). "The results of cytokine secretion showed that although the percentages of IL-4-, IL-10-, and IL-12-secreting DCs from WT mice increased significantly after infection (P < 0.05), no marked difference was found between infected WT and infected TLR7 KO mice (P > 0.05)." (PMID 34692568, 2021). "All turkeys that received vaccination and infection showed consequences on upregulation of TLR1B, TLR2B, TLR4, TLR6 and TLR7, whereas in chickens of the equivalent group, TLR1B, TLR2B and TLR21 were found to be increased in contrast to TLR4 and TLR7 which were decreased." (PMID 34579197, 2021). "Although TLR7 stimulation improved the effect of NUC on T cell responses, this was not sufficient to permit the acquisition of an optimal immune reactivity adequate to provide complete control of infection, as detectable after spontaneous control of self-limited acute infections." (PMID 34685543, 2021).